ALB (albumin)
Diseases named in the same sentence as ALB in open-access papers (continued):
Sharing a sentence is not in itself a finding about the gene and the disease.
diabetes (continued). "We found that preoperative albumin <3.5 g/dL, BMI ≥40 kg/m2, tobacco use, and diabetes were associated with increased risk of postoperative infection, readmission, any complication, and mortality." (PMID 34277906, 2021). "Using the same analytic strategy, we identified the presence of NASH, diabetes, overweight, blood platelets count, albumin, and HBV DNA level as independent factors associated with severe fibrosis." (PMID 35111690, 2021). "Epidemiological studies found that higher serum calcium levels and albumin-corrected calcium levels were associated with an increased risk of developing metabolic syndrome, diabetes, and hypertension." (PMID 34434908, 2021). "We found that preoperative albumin <3.5 g/dL, BMI ≥40 kg/m2, tobacco use, and diabetes were all individually associated with increased risk of postoperative complications." (PMID 34277906, 2021). "The presence of diabetes, low albumin levels, and higher HBA1c are associated with postoperative complications and lead to lower PCS and MCS scores." (PMID 34926097, 2021). "Age, sex, chronic obstructive pulmonary disease, diabetes, heart failure, coronary heart disease, intensive care unit treatment, in-hospital thrombotic events, D-dimer, C-reactive protein, troponin, and albumin levels were associated with mortality." (PMID 34218413, 2021). "Univariate Cox regression analysis demonstrated that factors including diabetes as the primary disease, gender, age, serum albumin levels, and place of residence were associated with technique failure." (PMID 34233593, 2021). "Although nephrologists and cardiologists have been paying attention to the study of proteinuria for years, type 2 diabetes mellitus (T2DM) is currently considered a condition in which increased urine albumin excretion ascertainsthe highest cardio-renal risk." (PMID 33673215, 2021). "Even when sex, age, BMI, pulse pressure, diabetes, hypertension, serum albumin, and hemoglobin were adjusted for, the risk of sarcopenia increased approximately 1.5 times in patients with eGFR < 45 mL/min/1.73 m2." (PMID 34531464, 2021). "Stage of disease, cause of disease, recent diagnosis of diabetes mellitus and serum albumin value were found to be significant predictors of undernutrition among the CKD patients." (PMID 34237068, 2021). "After 20 years, the incidence rate declines so that people with normal renal function and normal urinary albumin excretion after 30 years of type 1 diabetes mellitus (T1DM) are at lower risk of developing DN." (PMID 34307650, 2021). "In the bivariate analysis, both 30- and 60-days mortality were significantly associated with older age, hypertension, heart disease, diabetes, low albumin levels and high CRP to albumin ratio (CAR)." (PMID 34940406, 2021). "In the multivariable analysis, older age, smoking status, the presence of diabetes mellitus and coronary artery disease, and low albumin levels were still independently associated with adverse CV events." (PMID 32286459, 2020). "Plasma endocan level was inversely associated with BMI, diabetes mellitus, albumin, glucose, total cholesterol, and triglyceride." (PMID 33352837, 2020). "Glycoxidized albumin was associated with metabolic disorders observed in diabetes mellitus, such as retinopathy, nephropathy and coronary artery disease." (PMID 32408712, 2020). "The presence of diabetes and low serum albumin levels were risk factors for low GS (adjusted OR of 2.12, 95% CI of 1.16–43.86 and adjusted OR of 3.37, 95% CI of 1.32–8.62, respectively) but not for low HS." (PMID 32375664, 2020). "In contrast, the association between urine albumin and diabetes mellitus was already observed in previous studies, and it is consistent with the positive association detected by our study." (PMID 32008434, 2020). "Diabetes caused a two-fold increase in urinary albumin excretion while a similar increase was also observed in the diabetic mice treated with the vehicle of dabrafenib." (PMID 32591618, 2020).
diabetes (continued). "Elevated triglyceride, current or past cigarette smoking, and higher urinary albumin excretion were found to be independently associated with plasma FN-EDA in diabetes patients." (PMID 32499562, 2020). "Glycated albumin is not only useful for short-term diagnosis and monitoring but predicts the risk of diabetes, even in the presence of euglycemia." (PMID 33187372, 2020). "Factors associated with urinary albumin to creatinine ratio in participants with type 2 diabetes mellitus." (PMID 33362965, 2020). "Glycated albumin (GA) is a marker of short-term glycemic control and is strongly associated with the occurrence of diabetes." (PMID 33036613, 2020). "For the diabetes patients, American diabetes association suggested that the urinary albumin should be assessed at least once per year." (PMID 33228616, 2020). "Glycated albumin (GA), a marker of shorter-term (2–4 weeks) glycemic control, is strongly associated with the occurrence of diabetes." (PMID 33036613, 2020). "A total of 74 studies were included in the present review, extracted using combinations of the following keywords: glycated albumin, diabetes, dyslipidemia, obesity, kidney disease, cardiovascular risk, and therapy." (PMID 33187372, 2020). "Age, PD, diabetes mellitus, congestive heart failure, low serum albumin and high GGT levels are risk factors for peptic ulcers among ESRD patients." (PMID 33092560, 2020). "Multivariable logistic regression analysis showed increased age, male, low BMI, and increased HbA1c, combined with diabetic nephropathy and decreased serum albumin levels, were risk factors associated with low muscle strength in diabetes patients." (PMID 33204732, 2020). "These diets control weight and prevent hypertension, diabetes and urinary albumin, thus improving kidney function and reducing the risk of kidney damage." (PMID 33003345, 2020). "Ongoing studies also show that diabetes, high BMI and low postoperative albumin are risk factors for postoperative AKI." (PMID 32140301, 2020). "Early clinical diagnosis of DN is usually based on the presence of microalbuminuria (30–300 mg/day) or by the urinary albumin to creatinine ratio (> 30 mg/g of creatinine)." (PMID 32194418, 2020). "Patients with diabetes or high PG-SGA score or low perioperative albumin will have increased risk factors of AL, which should be paid enough attention in the perioperative period and nutritional support should be provided as soon as possible." (PMID 32461995, 2020). "Based on the results of P value of interaction, we further divided patients into subgroups, according to traditional risk factors, including age, sex, BMI, albumin, and diabetes." (PMID 31388342, 2019). "In conclusion, the present study evaluated the association between sarcopenia and urinary albumin level, urinary protein level, and eGFR via the meta-analysis of studies on diabetes." (PMID 31828155, 2019). "For glycemic control in patients with diabetes on peritoneal dialysis (PD), the level of glycated albumin (GA) associated with mortality is unclear." (PMID 30824808, 2019). "Low RMC use was defined as lack of a physical exam within one year among participants with CKD (estimated glomerular filtration rate < 60 mL/min/1.73m2 or urine albumin-to-creatinine ratio > 30 mg/g) or CKD risk factors (diabetes or hypertension)." (PMID 30630437, 2019). "Increased cardiovascular mortality was associated with increased age, diabetes, coronary artery disease, stroke, decreased albumin and total cholesterol, increased UT, and %MAP > 50%." (PMID 31766504, 2019). "The objective of the present study was to investigate the association between sarcopenia and urinary albumin level, urinary protein level, and estimated glomerular filtration rate (eGFR) in patients with diabetes." (PMID 31828155, 2019). "Chen and colleagues found that diabetes, congestive heart failure, and low albumin levels were risk factors for peptic ulcers in patients receiving dialysis." (PMID 31700754, 2019).
diabetes (continued). "The urinary albumin-to-creatinine ratio (UACR) plays a role in predicting the future risk of diabetes mellitus." (PMID 31569548, 2019). "Our aim was to investigate the association between the serum albumin levels and clinicopathological features and renal outcomes in patients with type 2 diabetes mellitus (T2DM) and biopsy-proven DN." (PMID 30911552, 2019). "Female gender, estimated glomerular filtration rate, age, physical activity, and smoking are positively associated with urinary nitrates whereas urine albumin/creatinine ratio, body mass index, and diabetes were inversely associated with urinary nitrates." (PMID 41163846, 2019). "Leakage of albumin is caused by the involvement of the glomeruli in the initial stages of the disease due to common causes such as diabetes and hypertension." (PMID 31382902, 2019). "Male sex, older age, underlying diabetes and hypertension, lower serum albumin and plasma hemoglobin, more frequent radio‐contrast exposure, entrance of clinical trials, and receiving chemotherapy were associated with AKI occurrence." (PMID 30968593, 2019). "A prediction model including eGFR, serum albumin level, and diabetes mellitus was developed, and risk scores ranged from 0 to 6 points." (PMID 31057617, 2019). "HIV (crude regression coefficient -3.96; CI -5.79–-2.13; p<0.001) and diabetes (coefficient -5.06; CI, -7.72–-2.40; p<0.001) were significantly associated with monthly serum albumin levels on univariate linear regression analysis." (PMID 31181128, 2019). "The present study investigated the association between sarcopenia and urinary albumin level, urinary protein level, and eGFR in patients with diabetes via a meta-analysis of observational studies." (PMID 31828155, 2019). "Further investigation of the effects of sex on the association between sarcopenia and urinary albumin level in patients with diabetes, including the mechanism involved, is needed." (PMID 31828155, 2019). "The present study investigated the association between sarcopenia and urinary albumin level, urinary protein level, and eGFR in patients with diabetes via the meta-analysis of observational studies." (PMID 31828155, 2019). "The relationship between renal albumin loss and cardiovascular risk in different groups of patients with increased vascular damage (hypertension, diabetes) has been demonstrated." (PMID 29682152, 2018). "STZ-induced diabetes is associated with increased kidney weights, albumin excretion rate (AER), and albumin creatinine ratio (ACR) due to the accumulation of extracellular proteins and kidney damage." (PMID 30009183, 2018). "One of the most notable findings in this study was the prevention of diabetes-induced urine albumin excretion in VASH2-deficient mice." (PMID 29641565, 2018). "Cardiovascular disease, diabetes, stroke, and low albumin concentrations were shown to be significantly associated with frailty in previous studies 25,26." (PMID 29451618, 2018). "Several patient-related characteristics, including advanced age, female sex, low serum albumin and comorbid diseases such as diabetes, are associated with high CVC use." (PMID 29609535, 2018). "Multivariable logistic regression analysis performed for four variables (age, male sex, history of diabetes mellitus, and serum albumin), indicated only younger age to be an independent risk factor for ARC (OR, 0.94; 95% CI, 0.91–0.96)." (PMID 30532142, 2018). "Older age, diabetes mellitus, cardiovascular disease and malnutrition (lower serum albumin and serum creatinine) were associated with both frailty and cognitive impairment among patients on CAPD." (PMID 30470776, 2018). "After additional adjustment for HbA1c, BMI, and duration of diabetes (model 4), the association between urinary albumin and all-cause mortality remained significant (HR = 1.32, 95% CI = 1.03–1.70, p = 0.031)." (PMID 30142885, 2018).
diabetes (continued). "Several risk factors, such as elevated CRP level, low albumin level, older age, low BMI, and diabetes mellitus, have been reported to be associated with early mortality after PEG." (PMID 29954339, 2018). "We further examined the effect of serum albumin on the risk for progression to overt diabetes in prediabetic subjects." (PMID 28430803, 2017). "Serum autoantibodies in type 2 diabetes patients showed preference of Amadori-albumin that suggests a causal role for Amadori-albumin in the pathogenesis of diabetes mellitus." (PMID 28192530, 2017). "Another study found that snoring was linked to a persistent increase in urinary albumin, a risk factor for diabetes." (PMID 29072591, 2017). "The link between suPAR, albuminuria and diabetes together with the finding of a predictive value for CKD intrigued us to assess the potential of suPAR in predicting onset of albumin excretion in patients at risk for type 2 diabetes." (PMID 28091558, 2017). "Increased age, elevated fibrinogen, decreased albumin, diabetes mellitus, hyperTG, and worse virological control were risk factors for renal impairment." (PMID 28906351, 2017). "When total subjects were divided two subgroups according to the age of ≥ 60 which had highest prevalence of diabetes, increase in serum albumin concentration was still significantly associated with lower risk of prediabetes development." (PMID 28430803, 2017). "Patients with type 2 diabetes mellitus and elevated urinary albumin:creatinine ratio (ACR) have increased risk of heart failure." (PMID 28716801, 2017). "In another USRDS study, risk factors for infection-related hospitalizations were found to be age (higher risk with increasing age), sex (higher risk for females), history of diabetes, heart failure and pulmonary disease, as well as low serum albumin." (PMID 28700621, 2017). "Albumin glycation and subsequent formation of advanced glycation end products (AGEs) correlate with diabetes and associated complications." (PMID 28520799, 2017). "The current study also showed that diabetes, higher BMI, and lower postoperative albumin are risk factors for postoperative AKI." (PMID 29028816, 2017). "Inhibition of VEGFA at the onset of diabetes abolished the associated diabetes-glomerular hyperfiltration, glomerular hypertrophy, and urinary albumin excretion in the type I diabetes model." (PMID 28774305, 2017). "While, presence of diabetes (HR 1.627, P = 0.001), presence of cardiovascular disease (HR 1.847, P < 0.001) and lower serum albumin level (HR 0.720, P = 0.023) were risk factors for late mortality (over 24 months)." (PMID 27576771, 2016). "Third, two Met residues in serum albumin showed elevated [Met(O)]/[Met] in patients with type 2 diabetes, diabetes-associated chronic renal failure and smokers, reflecting the altered oxidative stress status present in these conditions." (PMID 27929071, 2016). "Multivariate analysis showed that baseline eGFR, diabetes mellitus, and low serum albumin were significant risk factors for CT-CIN." (PMID 27149474, 2016). "[Met(O)]/[Met] levels of two residues in serum albumin were elevated in type 2 diabetes, diabetes-associated chronic renal insufficiency and chronic smoking." (PMID 27929071, 2016). "In this study, we also demonstrated that older age, lower albumin level, diabetes diagnosis and residual renal function were risk factors for patient mortality and technique failure." (PMID 27733978, 2016). "Multivariable linear regression analyses showed that proteinuria was associated with eGFR, uric acid, serum albumin, diabetes mellitus, age, clinic-SBP and triglyceride." (PMID 27775590, 2016). "In the univariate regression analysis, baseline albumin level had a statistically significant inverse association with age, female sex, diabetes, Ca level, and CT ratio." (PMID 27542730, 2016).
diabetes (continued). "Hypochlorite-modified albumin (HOCl-alb) has been linked to endothelial dysfunction, which plays an important role in the development of hypertension, diabetes, and chronic kidney disease." (PMID 26881015, 2016). "In multivariate Cox proportional hazard regression analysis, male, diabetes, congestive heart failure, diuretics use, diastolic BP, and levels of hemoglobin, protein, albumin, bilirubin, and BUN were associated with AKI development." (PMID 27622451, 2016). "Fructosamine and glycated albumin are even being considered as diagnostic markers of pre-diabetes and diabetes." (PMID 27896233, 2016). "Increased urinary albumin excretion in diabetes not only signals nephropathy but also serves as a risk marker for cardiovascular disease." (PMID 27057866, 2016). "While, presence of diabetes (HR 1.627, 95% CI 1.213–2.181, P = 0.001), presence of cardiovascular disease (HR 1.847, 95% CI 1.378–2.475, P < 0.001) and lower serum albumin level (HR 0.720, 95% CI 0.543–0.956, P = 0.023) were risk factors for late mortality." (PMID 27576771, 2016). "In this study, the baseline serum albumin level was found to be inversely associated with age, female sex, diabetes, Ca level, and CT ratio." (PMID 27542730, 2016). "In this study, urinary KIM-1 levels, along with urinary albumin excretion and the duration of diabetes, were found to be independent risk factors associated with low GFRs." (PMID 27293888, 2016). "Diabetes-associated renal injury was characterized by albuminuria (albumin:creatinine ratio, db/+: 3.2 ± 0.6 vs. db/db: 12.5 ± 3.1*; *P<0.05), increased glomerular/mesangial surface area, and kidney hypertrophy." (PMID 27649495, 2016). "It has been reported that approximately 40 % of patients with type 2 diabetes mellitus have elevated urinary albumin excretion consistent with underlying renal disease, and 17 % of patients with diabetes have CKD." (PMID 27184495, 2016). "The results indicated that diabetes caused a significant decrease in serum TP (P=0.000) and albumin levels (P=0.001), but their levels were significantly reversed by the oral administration of RJ." (PMID 27602318, 2016). "A previous study of non-GFR factors associated with cystatin C concentrations found diabetes mellitus, increased C-reactive protein, increased white blood cell count, and decreased albumin concentrations to be independently predictive of increased cystatin C." (PMID 27293926, 2016). "The multivariate analysis revealed that baseline eGFR (odds ratio [OR], 0.955; P < 0.001), a history of diabetes mellitus (OR, 2.583; P = 0.008), and the serum albumin level (OR, 0.449; P = 0.005) were associated with an increased risk of CT-CIN." (PMID 27149474, 2016). "In the control group, many high-risk subgroups (for example, male sex, diabetes, hypertension, high sagittal diameter, high insulin, high glucose, high urine albumin excretion) had a higher incidence of albuminuria than the corresponding low-risk subgroups." (PMID 24798033, 2015). "Patients’ age, diabetes mellitus and smoking habit were all positively associated with a significant increased risk of mortality in our PD patients, while serum albumin levels and residual diuresis were negatively correlated." (PMID 25885318, 2015). "Older age, a higher CRP, a lower albumin concentration, a history of cardiovascular disease and diabetes mellitus also showed an association." (PMID 25823004, 2015). "It is also well established that enhanced albumin glycation with diabetes is associated with the early occurrence of vascular complications, together with functional protein alterations." (PMID 25878764, 2015). "Definitions of abnormalities in albumin excretion were according to the latest guidelines of American Diabetes Association’s Standards of Medical Care." (PMID 26607500, 2015). "Apart from these factors, age, serum albumin, diabetes, and hypertension were also associated with mortality on univariate analysis." (PMID 26262995, 2015).